IL1B (interleukin 1 beta)
Diseases named in the same sentence as IL1B in open-access papers (continued):
Sharing a sentence is not in itself a finding about the gene and the disease.
infection (continued). "Our above observations showed that caspase-11 did not contribute to IL-1β secretion upon infection with El Tor V. cholerae, suggesting that CT-mediated cytosolic entry of LPS does not play a role in inflammasome activation by this biotype." (PMID 31736941, 2019). "These striking differences in fungal burdens were recently found to be due to candidalysin-dependent induction of IL-1β and CXCL1 secretion from CARD9+ microglial cells, which function to recruit CXCR2-expressing neutrophils to the brain to control the infection and hence reduce fungal burdens." (PMID 31401652, 2019). "As expected, KCl, but not NaCl treatment inhibited IL-1β and Casp1 p20 production in response to infection, confirming the participation of the NLRP3 inflammasome in human cells." (PMID 31754185, 2019). "Infection with either strain of RV caused decreases in DUSP10 expression at the mRNA and protein levels which were not seen in response to IL-1β." (PMID 30333178, 2019). "When infection experiments were performed in the presence of glyburide, a compound that inhibits NLRP3 inflammasome, or A151, a specific AIM2 inhibitor, the secretion of IL-1β was significantly inhibited with respect to uninfected controls." (PMID 32038610, 2019). "Both time periods of 5% oxygen incubation were sufficient to increase levels of il-1β:GFP in the absence of infection to a similar extent to both hydroxylase inhibition and DA Hif-1α." (PMID 30552162, 2019). "In V. vulnificus-infected fish, Epinecidin-1 could also regulate immune response genes such as IL-10, IL-1b, TNF-α, and IFN-γ and help to control the infection by enhancing the immunity." (PMID 31138331, 2019). "If a NADase cleavage product mediates inhibition of P2X7-dependent IL-1β release, then the addition of them during nga(G330D) infection (where they should not be generated by the bacteria) should lead to a decrease in IL-1β." (PMID 31275321, 2019). "IL-1β is detectable in bronchoalveolar lavage (BAL) fluid from children with CF and is strongly correlated with neutrophil counts, independent from detectable infection." (PMID 31532390, 2019). "On the other hand, olmesartan decreases IL-1β and TNF-α and increases IL-10, which could help the parasite establish an infection by decreasing the levels of proinflammatory cytokines." (PMID 31666114, 2019). "We found that apocynin effectively blocked ROS production upon infection with MAYV or PMA stimulation, and this effect resulted in a dose-dependent blockage of IL-1β secretion induced by MAYV infection." (PMID 31479495, 2019). "In contrast to the IL1 receptor antagonist (IL1ra, anakinra), canakinumab acting selectively on IL1B but not on IL1A did not affect the host defences and susceptibility to the infection to such a large extent." (PMID 31780867, 2019). "Under these conditions, 3 hours after PAO1 infection alone, but not LL-37 alone, exposure had promoted a significant release of IL-1β." (PMID 30978238, 2019). "We confirm increased production of Th1 cytokines IFNγ, TNF, IL-12, IL-23, and IL-1β in the proximal ileum in B6 mice upon infection, while absence of IL-33R/ST2 attenuated the Th1 cytokine response." (PMID 31057534, 2019). "In our study, we show that stabilization of Hif-1α upregulates proinflammatory macrophage il-1β expression in the absence of an infection challenge." (PMID 30552162, 2019). "Infection with VSV or EMCV generates NLRP3 inflammasome activation and ensuing IL-1β release." (PMID 31024004, 2019). "Under these conditions, bacterial colonization was similar to experiments where pumps were filled with PBS indicating that Il-1β is not essential for the maintenance of the biofilm infection." (PMID 31156635, 2019). "Furthermore, it has been described that in vitro DENV-infection of macrophages induces an inflammatory response through activation of the NLRP3 inflammasome, leading to the release of IL-1β." (PMID 30901375, 2019).
infection (continued). "In addition, we examined whether infection led to the induction of proinflammatory cytokines, finding significantly increased transcription of the Tnf-α and Il-6 genes as well as significantly elevated protein levels for IL-1β and IFN-γ as determined by ELISA of cecal protein lysates." (PMID 31848276, 2019). "The comparative analysis of the expressed values for IL-1β and NOS2 were statistically different between the assays, compared to the attenuated and virulent strains, differing when compared to the control groups and infection with the saprophytic strain." (PMID 31800570, 2019). "Our data identify an early proinflammatory response, involving macrophage il-1β expression, that is important for the onset of early disease but ultimately fails to control infection leading to granuloma formation." (PMID 30552162, 2019). "The STAT3 targets that increased in the early infection were mainly inflammatory regulators including pro-inflammatory factors IL1B, IL6 and immunosuppressive factor IL10, which might contribute to the immune regulatory role of glia in CNS during infection." (PMID 31575039, 2019). "The results demonstrated significant upregulation (P < 0.05) of IL-1β mRNA at 7 and 10 days after lethal infection compared to the level after nonlethal infection." (PMID 31570561, 2019). "Among them, Cxcl1, Cxcl2, Cxcl3, Cxcl10, IL1b, Socs3, and Mmp14 were overexpressed more than 100-fold compared with the non-infected sample regardless of infection type." (PMID 30858471, 2019). "While IL-1α and IL-1β levels in WT and IL-1R−/− mice were similar, levels of IL-6, IL-12p70, IFN–γ, CCL2, CCL3, and CXCL9 were significantly lower in IL-1R−/− mice compared with wild-type mice following infection with P1/7 (p < 0.05)." (PMID 31262357, 2019). "Infection performed in macrophages derived from Nlrp3–/–, Aim2–/–, Asc–/–and Casp1/11–/–mice indicate that the NLRP3, but not AIM2 inflammasome is essential for production of inflammatory cytokines, such as IL-1β." (PMID 31479495, 2019). "DA Hif-1α was not sufficient to reduce M. marinum infection levels when il-1β expression was blocked, suggesting that the il-1β response to M. marinum infection is critical to control infection." (PMID 30552162, 2019). "Interestingly, the increased peak of IL‐1β and IL‐6 in Ma.24‐infected RAW264.7 was earlier than Ms13 infection at 3 hours." (PMID 31596045, 2019). "Similarly, following infection with H3N2, all groups produced measurable levels of IFN-λ, IL1-β, IL-8, IP-10 and MIP1- α." (PMID 31747925, 2019). "In PAD patients, pro-inflammatory IL-1β or TNF-α, and endotoxins, are frequently increased as a consequence of the inflammation and infection at the level of the foot, and these cytokines may stimulate SOCS proteins, promoting a GH insensibility." (PMID 29346331, 2018). "In contrast, acute infection of human primary fibroblasts with ZIKV revealed that the virus induces specific activation of inflammasome components such as AIM2 and interleukin-1β (IL-1β)." (PMID 30453621, 2018). "We also observed reduced IL-6 expression in IFNAR KO BMDMs at 36 h after infection and enhanced IL-1β secretion in BMDCs lacking IFNAR." (PMID 30233599, 2018). "Infection with type I or type III strain parasites did not drive IL-1β expression on its own, indicating that the parasites are not able to provide the normal priming step." (PMID 30154263, 2018). "Nec-1 treatment drastically reduced IL-1β production in response to the Sk02 infection in a dose-dependent manner, while not impairing the pro-IL-1β expression." (PMID 30096906, 2018). "Therefore, the diminished fungal loads observed at weeks 6 and 10 post-infection have possibly triggered diminished macrophages and dendritic cells NLRP3 activation and reduced IL-1β production." (PMID 30410119, 2018).
infection (continued). "Similar to other investigators, IL-1β synthesis is markedly upregulated in the lower tract of C57BL6 mice during early C. muridarum infection, where the neutrophils and macrophages are thought to be the primary sources of this cytokine during infection." (PMID 29624589, 2018). "By using this novel model, the authors demonstrated that PBECs were inert to direct Mtb-infection and not potent responders in an IL-1β- and type I interferon- (IFN-) mediated Mtb-activated immune network." (PMID 30356420, 2018). "Indeed, infection with B. abortus triggers the production of mtROS in BMDM after 17 h and contributes to the secretion of IL-1β in an NLRP3-dependent manner." (PMID 29581535, 2018). "Compared to those of mock infection or VR2332c, JA142c and poly I:C induced significantly increased transcript levels of IFN-β and pro-inflammatory cytokines (IL-1α, IL-1β, IL-6, IL-8, IL-12, and TNF-α) at either two or all three time points assayed (12, 24 and 36 hpi)." (PMID 30509265, 2018). "Based on these findings we hypothesize that the activated microglia in μBS play a potential role in enhancing the expression of pro-inflammatory cytokines such as interleukin (IL)-1β, IL-6, and TNF-α in response to ZIKV-BR infection." (PMID 30619100, 2018). "At lower infection doses, significant differences in height and kinetics of cytokine concentrations in BAL-f were mostly confined to the time point around the maximum cytokine response (2–4 h for IL-1β and Ccl3, 2–8 h for TNF, 8–24 h for Cxcl-1, Ccl2)." (PMID 29734720, 2018). "The association of TAK1 with the proteins was not affected within 40 min of infection with H. pylori or 10 min of stimulation with TNF or IL-1β." (PMID 29581850, 2018). "We showed that aged mice express higher levels of IL-1β and OPN prior to infection compared to their younger counterparts, and this pro-inflammatory state that comes with aging impairs the antiviral response in those mice when they are exposed to RSV infection." (PMID 29677209, 2018). "Here we extend these observations, further exploring the strength of these correlations over time and asking if the infection-induced deficits in theta burst L-LTP and mBDNF will also subside and follow the same time course of recovery as the alterations in IL-1β and memory." (PMID 29911174, 2018). "At the same time, indicators of inflammatory response such as production of IFN-γ, TNF-α, IL-1β, and IL-6 mediated by TLR/MyD88/NFκB were also activated after N67 infection, which may explain the pathology and host death later in infection." (PMID 30327482, 2018). "Examination of the gingivae for pro and anti-inflammatory cytokine expression 4 days post infection revealed that treatment with RvD2 maintained tissue homeostasis by preventing increased expression of the pro-inflammatory cytokines, such as IFN-γ, IL-1β, and TNF-α and decreased expression of IL-10." (PMID 29922275, 2018). "Meanwhile, ΔGntR infection increased the levels of IFN-γ, IL-1β, and TNF-α, indicating ΔGntR could induce the secretion of inflammatory but not anti-inflammatory cytokines IL-10." (PMID 29435171, 2018). "MG groups had higher levels of TNF-α, IL-1B, and IL-6 compared to no-infection groups (both miR-451-M and miR-451-Inh), as a result of the higher gga-miR-451 expression in the MG group." (PMID 29652844, 2018). "THP-1 cell infections with T. gondii show GRA15-dependent and strain-specific IL-1β production." (PMID 30301855, 2018). "This ligand has been shown to induce an inflammatory response in absence of infection as well as is responsible for the stimulation and release of IL-1β from monocytes." (PMID 29867970, 2018). "Following H37Rv infection, we found increased levels of mature CTSB, cleaved caspase-1, and mature IL-1β from infected macrophages, the latter observation confirming that the changes in IL-1β levels measured by ELISA reflect alterations in the mature cytokine." (PMID 29977244, 2018).
infection (continued). "Our data suggested that NOD2 activity began to increase in brain tissue 12 h after infection, while those of IL-1β, TNF-α, and IL-6 showed no obvious changes at 12 h." (PMID 30186539, 2018). "Our investigations thus far have revealed that infection induced production of prostaglandin E2 or of infection-induced necrosis are not, however, regulated by TG levels (data not shown) even though IL1β expression in our model is dependent on TGs." (PMID 30018616, 2018). "The serum IL-1β level reached a peak at 18 d in the BPG treatment subgroup and at 21 d in the no BPG treatment subgroup, before returning to normal levels [i.e., not significantly different from the blank group level (P > 0.05)] at 42 d post-infection." (PMID 29490620, 2018). "In the absence of IL-10, macrophages were able to produce IL-1β and NO in response to infection with A54970 strain, in the same levels as induced by BMDMs infected with A28006." (PMID 30518854, 2018). "Recognition of T. cruzi by the innate and adaptive immune cells trigger the production of cytokines, such as IL-1β, IL-18, IL-6, TNF, and IL-10 during the acute phase of infection which exert profound effects in the killing of parasites and in the modulation of inflammation." (PMID 29774028, 2018). "From these studies, IL-1β was found to be markedly upregulated in the presence of SLS, and further investigation revealed that this cytokine contributes to cytotoxicity in human keratinocytes during infection." (PMID 30018884, 2018). "When the infection was mostly cleared in WT mice (day 9), we observed a decrease in most chemokines, but not in IL-1α and IL-1β, CCL7, and CCL4." (PMID 30102746, 2018). "As treatments with the p38 inhibitor, SB203580, and the NFκB inhibitor, curcumin, prior to infection were able to almost completely abrogate IL-1β production during GAS infection, we concluded that IL-1β is, indeed, produced in response to activation of this inflammatory pathway." (PMID 30018884, 2018). "Surprisingly, we found that in wild-type cells, IL-1β treatment, in the absence of infection, drove the transcription of IFN-β and ISGs at late times following treatment." (PMID 29559569, 2018). "The activated microglia/macrophages seen in the sham IL-1β group was not related to infection because no late infiltration of neutrophils was found in this group." (PMID 29690837, 2018). "The mRNA levels of ileal Tnfα, Il-1β, Il-22, Il-10, Foxp3 and RegIIIγ were comparable between Tac and Jax mice regardless of infection status." (PMID 29789574, 2018). "It is also known that HIF-1 expression is upregulated in response to inflammatory stimuli including IL-1β, TNF, and bacterial products through pathways involving NF-kB, highlighting an interdependence of the innate immune and hypoxic responses to infection and tissue damage." (PMID 30250643, 2018). "Similar to airway epithelial cells, human macrophages express type I and type III IFNs, IL-1α, IL-1β, IL-6, TNF-α, CXCL8, CCL2 (MCP-1), CCL3 (MIP-1α), CCL4 (MIP1-β), CXCL9, and CXCL10 following infection with seasonal H1N1 or with H5N1, 2009 H1N1 strains demonstrating increased pathogenicity." (PMID 29623073, 2018). "Pb significantly increased the infection-induced increase in serum IL-1b when compared with the infection in mice not exposed to Pb." (PMID 29925772, 2018). "Through the first four days of infection and co-treatment with eritoran, viral titers did not notably decrease; however, pro-inflammatory cytokines and chemokines, such as TNF-α, IL-1β, IL-6, and CXCL1 were mitigated during this early infection and the IAV infection resolved more rapidly." (PMID 29988424, 2018). "Minimum adequate models (MAMs) for effects of infection with Mycoplasma gallisepticum isolates VA1994 and NC2006 on house finch expression of cytokines IL1B, IL6, IL10, CXCLi2, and TNFSF15 in internal eyelid (nictitating membrane) across three different time points." (PMID 29403495, 2018).
infection (continued). "Nematode infection did not result in Il1b expression by peritoneal macrophages but both LPS injection and Salmonella Typhimurium infection resulted in a robust induction of Il1b expression." (PMID 29343442, 2018). "In these experiments, we infected BMDM with H37Rv and ΔESAT6 H37Rv strains in the presence or not of the LFn-ESAT-6/PA complex and then measured IL-1β production 24 h post-infection." (PMID 29977244, 2018). "IL-1β promotes APC-stimulatory activity and the upregulation of adhesion receptors on immune and endothelial cells as a prerequisite for the infiltration of leukocytes to sites of infection in acute inflammation." (PMID 30042333, 2018). "One study found that IL-1β−/− mice do not develop UTI upon infection, suggesting that IL-1β produced by the host is crucial for bacterial colonization." (PMID 29662840, 2018). "A28006 infection induces increased amounts of IL-1β production, while infection with A54970 strain induces no production of this mediator." (PMID 30518854, 2018). "Taking into account that during the acute infection with the Tulahuen strain, the liver of B6 mice displays cellular infiltrates with predominance of macrophages, we decided to analyze the induction of NLRP3 inflammasome and IL-1β within these cells." (PMID 29774028, 2018). "To address this hypothesis, we performed subcutaneous infection of transgenic mice with wild-type GAS and assessed IL-1β production in the skin tissue and plasma at 24, 48, and 72 h post-infection." (PMID 30018884, 2018). "For example, IL1-β (gene IL1B) and IL23, which were markedly induced by Mtb in our infection model, are known to induce group 3 ILC (ILC3); IL15 among others activates ILC1 cells, and IL1-β, thymic stromal lymphopoietin (TSLP) and IL33 are prominent activators of ILC2 cells." (PMID 29977236, 2018). "Indeed, we found the proinflammatory cytokines IL-1β, TNF, and Ccl3 reduced in BAL-f of ExoY-infected mice as compared to ExoYK81M-infected mice at 2–4 h after infection." (PMID 29734720, 2018). "Notably, we found that IL-1β levels were significantly increased in both lung homogenates and BALF of mice at 3 and 7 days after intratracheal infection with B. abortus." (PMID 30456207, 2018). "Furthermore, in vitro infection of bone marrow-derived macrophages with E. coli strains ST150 and ST375 induced comparable IL-6 and IL-1β production." (PMID 30356663, 2018). "RT-qPCR analysis revealed that at 6 h of infection, hyphae and, to a lesser extent, conidia induce Il1b and Tnfa, but not il18 transcripts in BMDMs." (PMID 29209318, 2017). "Casp1Null BMDMs did not secrete IL-1β and IL-18 in response to infection by E. coli and C. rodentium or transfection of LPS." (PMID 28345580, 2017). "In addition, the immune related genes RIG-1, IFN-β, IFN-γ, IL-1β and IL-6 were differentially regulated by CH60 or H strain infection in the lung (P<0.001 or P<0.01)." (PMID 28614378, 2017). "The concentration of IL-1β and IL-23 in the BALF was significantly improved at the early stage of infection, which might promote the secretion of IL-17A by γδT cells." (PMID 28912779, 2017). "Detection of IL-1β and TNF-α levels in serum samples of mice 48 h post-infection." (PMID 28129375, 2017). "Secretion of IL18, but not IL1B was induced by C. albicans, which is consistent with the pro-inflammatory nature of the infection." (PMID 28369145, 2017). "The 0.25 mM NaO treatment slightly decreased the IL-1β secretion, and the infection alone did not change this effect." (PMID 28361042, 2017). "We have further studied the expression of intracellular pro-IL-1β, IFN-γ, IL-4, IL-17, and TGF-β cytokines by CD4+ and CD8+ T cells in the lungs of infected WT, Nlrp3−/−, Casp1/11−/−, and ASC−/− mice at 48 h, 2, 4, and 10 weeks of infection." (PMID 28740491, 2017). "Notably, 1–2 h after infection, TAGLN2−/− mice showed higher plasma levels of TNF-α, IL-6, IL-1β, and IL-12 than wild-type mice." (PMID 28821818, 2017).